GDF15 (growth differentiation factor 15)
Diseases named in the same sentence as GDF15 in open-access papers (continued):
Sharing a sentence is not in itself a finding about the gene and the disease.
Obesity (continued). "Growth differentiation factor 15 (GDF15), a cytokine that enhances insulin sensitivity and reduces food intake, is a promising therapeutic target for obesity." (PMID 40530451, 2025). "Therefore, the increase in circulating levels of GDF15 during obesity could be a consequence and not a cause of it." (PMID 40530451, 2025). "Binding of GDF-15 on GFRAL has been shown to modulate appetite and energy intake and plays a role in obesity and cachexia." (PMID 38686386, 2024). "These neural networks are regulated by diverse appetite-regulatory hormones in which growth differentiation factor 15 (GDF15) has been identified as one of the key players in multiple metabolic disorders, such as obesity and diabetes." (PMID 38310105, 2024). "Our study uncovers novel data on the physiology of GDF15, GIP, and C-peptide in leanness, obesity, and MASLD." (PMID 38762719, 2024). "In the realm of adipose tissue, obesity, and hormones related to systemic metabolism, FGF21 and GDF15 have recently been recognized as important mediators of metabolic signaling between adipose tissue and other metabolic organs." (PMID 39000187, 2024). "These specific mechanisms make GDF15‐GFRAL pathway a potential target for treating many metabolic diseases, including obesity." (PMID 39700016, 2024). "In this review, we will explore how the GDF15‐GFRAL axis is regulated, its distribution in the body and its role in the regulation of metabolism, appetite and obesity." (PMID 39700016, 2024). "Given its distinctive mechanisms, the GDF15‐GFRAL axis represents an attractive target for addressing various metabolic disorders, especially obesity." (PMID 39700016, 2024). "We aimed to investigate the fasting and stimulated levels of GDF15, total and H-specific, glucose-dependent insulinotropic polypeptide (GIP) and C-peptide, in two physiology interventional studies: one focusing on obesity, and the other on MASLD." (PMID 38762719, 2024). "Indeed, GDF15 analogs, which try to overcome the pharmacokinetic (e.g., a short half-life of ~3 h in mice and non-human primates) and physicochemical (e.g., high aggregation propensity) limitations of native GDF15, have been developed for the treatment of obesity." (PMID 37513338, 2023). "Growth differentiation factor 15 (GDF15), a member of the transforming growth factor beta (TGF-β) superfamily, is involved in various pathophysiological processes such as anorexia, obesity, inflammation, and tumorigenesis." (PMID 38082448, 2023). "Therefore, GDF-15 could be a compensatory protective factor in obesity." (PMID 37152921, 2023). "Since high circulating GDF15 was positively correlated with cachexia, characterized by great loss of adipose tissue and skeletal muscle (sarcopenia), in some types of cancer patients, we examined whether CPT-induced GDF15 elevation causes sarcopenia in the context of obesity in our model." (PMID 35202387, 2022). "Although being a member of TGF-β superfamily, more and more evidence showed that GDF-15 has high affinity with GDNF family receptor α-like (GFRAL), which is correlated to anti-obesity effects and energy balance." (PMID 35963873, 2022). "Growth differentiation factor 15 (GDF15), also known as macrophage inhibitory cytokine-1, has emerged as a new anti-obesity target." (PMID 35202387, 2022). "Collectively, these results show that the anti-obesity effect of CPT is due to the suppression of food intake, which is consistent with the reported anorectic effects of GDF15." (PMID 35202387, 2022). "These evidences suggest that GDF15-GFRAL-RET is a central regulator of feeding and body weight and a new therapeutic target of both anorexia-cachexia and obesity." (PMID 34150865, 2021). "However, instrumenting genetic variants, including the ones found with the Olink assay, that are proxies for life-long higher GDF-15 levels in the physiological range did not provide evidence for a causal role of GDF-15 in measures of adult obesity and metabolic health." (PMID 34819519, 2021).
Obesity (continued). "While the exact role of GDF‐15 in the aging process is unclear, elevated GDF‐15 has been observed in other chronic inflammatory diseases, including cardiovascular disease, obesity, type 2 diabetes, and cancer." (PMID 33738380, 2021). "Growth differentiation factor-15 (GDF-15) and its receptor GFRAL are both involved in the development of obesity and insulin resistance." (PMID 33302552, 2020). "The role of GDF-15 and its receptor GFRAL in the development and progression of obesity and T2D is well described, but the molecular mechanisms accounting for the high expression of GDF-15 in these conditions is poorly understood." (PMID 33302552, 2020). "Actually, we did observe severe obesity, diabetes, and serious fatty liver in high-fat diet (HFD)-fed GDF15-/- mice when we first obtained three offspring." (PMID 32492819, 2020). "A significant effect of obesity was found, with obese ZSF1 rats showing higher GDF15 levels compared to their lean counterparts (P = 0.001)." (PMID 32374790, 2020). "It is not known whether GDF15 is associated with obesity-related outcomes." (PMID 32671100, 2020). "Growth differentiation factor 15 (GDF15), a marker of oxidative stress and the inflammatory process, is a stress-responsive hepatokine that is increased in obesity, glucose intolerance, and cardiovascular diseases." (PMID 30867412, 2019). "The following variables were significantly associated with the IL‐18 concentration at three out of the four occasions during follow‐up: male sex, obesity, diabetes and biomarkers of renal function (cystatin C), and inflammation (WBC, CRP‐hs, GDF‐15, Il‐10)." (PMID 31596518, 2019). "Our findings correlate with those observations as we found advanced age, DM, obesity (BMI >25 kg/m2), CRP and CKD were independent predictors of elevated GDF-15 in patients with CAD who needs PCI." (PMID 27056183, 2016). "GDF15/MIC-1 is widely distributed in mammalian tissues and has multiple functions in various pathologies including inflammation, cancer, and obesity." (PMID 27916875, 2016). "GDF15 plays multiple roles in various pathologies such as CVD, obesity, inflammation, and cancer due to its anti-inflammatory, antiproliferative, and antitumoral properties." (PMID 26090487, 2015). "Obesity induces chronic low-grade inflammation, which increases the secretion of proinflammatory cytokines such as tumor necrosis factor α (TNF-α), and chemokines, such as GDF-15." (PMID 41597417, 2026). "Although several studies have explored the relationship between GDF-15 and obesity, atherosclerosis, or heart failure, no study has simultaneously assessed all three conditions together." (PMID 41597417, 2026). "Given its multifaceted functions, GDF-15 is emerging as a viable target for non-pharmacological obesity interventions." (PMID 40725674, 2025). "Notably, a study utilizing human liver single-cell RNA sequencing has shown increased expression of GDF-15 across all hepatocytes, which supports the strong correlation between GDF-15 levels and non-alcoholic fatty liver disease (NAFLD) and obesity." (PMID 40722664, 2025). "In this study, we demonstrated that circulating GDF15 levels increase with obesity regardless of sex, with levels consistently higher in men." (PMID 40530451, 2025). "Transcripts for several candidate genes for obesity were absent in the whole brain or absent in specific regions of the brain (Cyp17a1, Gdf15, Gpr151, Lmx1b, Olig3, Sbk1, Sim1, Skor1, Tnni3k)." (PMID 39920851, 2025). "Furthermore, clinical studies have revealed that bitter-tasting drugs increase endogenous GDF15 expression in obese patients via bitter taste receptors (TAS2Rs) in the intestinal epithelium, suggesting that TAS2Rs may represent novel therapeutic targets for combination therapy in obesity." (PMID 40837873, 2025).
Obesity (continued). "For instance, a recent study observed that, in contrast to men, women exhibit a negative trend regarding the correlation of circulating GDF15 levels and obesity." (PMID 40530451, 2025). "Moreover, in obesity, membrane-bound matrix metalloproteinase 14 (MT1-MMP/MMP14) inhibits GDF15 signaling by blocking GFRAL." (PMID 41234361, 2025). "The current study is the first, to our knowledge, to assess GDF-15 alongside subjective appetite in males without obesity." (PMID 40410377, 2025). "The aim of this study was to investigate the impact of a single exercise session conducted prior to PKU-type meal on postprandial PYY, GLP-1, GDF-15, appetite and fat oxidation in a healthy population without obesity." (PMID 40410377, 2025). "GDF15 affects the energy metabolism of the body by activating the GFRAL receptor, e.g., it enhances fatty acid β-oxidation and reduces appetite thus preventing obesity as well as inducing cachexia and sarcopenia." (PMID 39643709, 2024). "The discovery of GDF15, a stress-responsive hormone for the non-homeostatic control of body weight, has created hope for the treatment of obesity." (PMID 38310105, 2024). "In that study, GDF15 levels in male and female patients with obesity (n = 20) did not change upon treatment with liraglutide for 5 weeks." (PMID 38965822, 2024). "A recent study in youth with overweight/obesity reported, without discriminating between total and H-specific GDF15, that GDF15 concentrations varied with alterations in liver fat content." (PMID 38762719, 2024). "Here, the authors show that artesunate, an FDA-approved treatment for severe malaria, can be repurposed for the treatment of obesity via GDF15/GFRAL signaling axis without overt side effects in mice and non-human primates." (PMID 38310105, 2024). "Unlike endogenous GDF15, the therapeutic potential of exogenous GDF15 in obesity and metabolic diseases has been demonstrated by numerous animal and preclinical studies." (PMID 39700016, 2024). "Because of the established role of brainstem-restricted GDF15–GFRAL signalling in feeding control, we tested whether the anorexigenic and anti-obesity effects of N-acetyltaurine administration requires an intact GFRAL receptor." (PMID 39112712, 2024). "In the absence of GDF15 or inhibiting its activity, mice exhibited increased diet intake and obesity, as well as poorer blood glucose levels, insulin levels and glucose tolerance." (PMID 39700016, 2024). "GDF15 level remained unchanged following treatment with liraglutide or lorcaserin in obesity patients, indicating that it does not directly participate in the metabolic feedback pathways activated by GLP1R agonists." (PMID 39700016, 2024). "Herein, both during fasting and following the ingestion of a high-fat meal over 3 h, we show that GDF15 is not significantly different between people with distinct weight status (leanness vs. obesity)." (PMID 38762719, 2024). "Long-term induction of GDF15 in this model was required to attenuate the progression of obesity by increasing energy expenditure, while FGF21 did not affect energy expenditure, but remarkably ameliorated DIO and insulin resistance." (PMID 37818094, 2023). "Decreased circulating levels of GDF-15 and FGF-21 were associated with greater weight loss at 1 year, regardless of the types of anti-obesity modalities." (PMID 37436597, 2023). "GDF15 treatment potently reduces food intake in ob/ob mice, and in non-human primates with spontaneous obesity." (PMID 37818094, 2023). "Pre-clinical studies administering recombinant GDF15 in rodents and non-human primates revealed the potential of GDF15 for the treatment of metabolic disorders such as obesity and diabetes." (PMID 37818094, 2023). "Although our recent results are in line with these findings, we have also found that, in contrast to men, women exhibit a negative trend regarding GDF15 correlation with obesity." (PMID 36992609, 2023).
Obesity (continued). "Therefore, the GDF-15/GFRAL axis is suggested as an essential part of energy homeostasis and BW regulation and is currently a novel therapeutic target for obesity." (PMID 37436597, 2023). "Similarly, among the 15 anti-inflammatory organokines, 7 (adiponectin, Omentin-1, ZAG, SFRP5, CTRP3, IL-10, and DEL-1) showed reduced levels and 8 (LCN2, VASPIN, IL-1RA, FGF21, GDF15, MANF, Irisin, and IL-6) showed elevated levels in patients with obesity." (PMID 35909571, 2022). "GDF-15 is considered as a major regulator of appetite through its hindbrain receptor glial-derived neurotrophic factor receptor alpha-like (GFRAL), and its plasma levels were found to be elevated in the context of obesity and diabetes." (PMID 35251002, 2022). "Recently, with the discovery of GDF15’s specific receptor glial-derived neurotrophic factor (GDNF) receptor alpha-like (GFRAL), enthusiasm is heightened in understanding this hormone’s regulation and exploring its therapeutic application in obesity treatment." (PMID 35202387, 2022). "GDF15 and FGF21 have been found to be associated with a range of non-mitochondrial diseases, including cancer, obesity, renal diseases, diabetes, liver diseases, and non-mitochondrial myopathies." (PMID 35498801, 2022). "Equally important, GDF-15 concentrations were not influenced by age, gender, or obesity, which are common confounding factors for other biomarkers, especially NT-proBNP." (PMID 36556311, 2022). "Overall, systemic CCL5, GDF15, and IGFBP6 levels declined following 12 months of anti-obesity therapy and weight loss, irrespective of a conservative or bariatric approach." (PMID 36430499, 2022). "•GDF15 and FGF21 synergistically protect against obesity-induced hepatosteatosis." (PMID 36064109, 2022). "Thus, GDF15 was proposed to be of therapeutic value in the management of IR, T2DM, and obesity through the modulation of metabolic activity of the lipolytic genes." (PMID 36444166, 2022). "Similarly, GDF15 transgenic mice fed a HFD show reduced NLRP3 inflammasome activity and pro-inflammatory macrophage infiltration into white AT as well as lower serum leptin and insulin levels, suggesting that GFD15 could reduce obesity-associated inflammation and improve insulin sensitivity." (PMID 35909571, 2022). "We confirmed the RNA-Seq data by qPCR and showed that DB, but not aloin, increased (P < 0.001) GDF15 expression in a concentration-dependent manner in jejunal crypts from patients with obesity." (PMID 34784295, 2022). "Therefore, larger longitudinal and interventional studies are warranted to shed light on the metabolic dynamics linking GDF15 and NAFLD in youth with overweight or obesity." (PMID 35194014, 2022). "Although the anti-inflammatory growth differentiation factor 15 (GDF-15) is a candidate protein against obesity, its mechanisms regulating the immune responses are not fully cleared." (PMID 34521901, 2021). "Using Gdf15-/- mice they showed that endogenous GDF15 was required for the weight-lowering actions of metformin in diet-induced obesity; however, they did not explore the source of GDF15 in vivo." (PMID 32310257, 2020). "Plasma GDF15 levels, when normalized to BMI categories displayed a severity-dependent relationship with obesity having the highest GDF15 in obesity Class-III patients, something we did not see with triglycerides (data not shown)." (PMID 32671100, 2020). "GDF15 protein was detected in all atrial samples but was not significantly different between obesity groups." (PMID 32671100, 2020). "GDF15/GRAL/RET signaling plays an important role in appetite control, and attempts to identify druggable targets in this pathway and develop related novel treatments for obesity or cancer-induced cachexia are ongoing." (PMID 32911810, 2020). "Several studies suggest that exogenous GDF15 exerts protective effects against obesity and insulin resistance, although the role of endogenous GDF15 in these diseases has not been clearly shown." (PMID 29717162, 2018).
Obesity (continued). "The pharmacological studies are consistent with previous reports of GDF15 transgenic mice being resistant to high fat diet-induced obesity (DIO) and glucose intolerance, supporting a therapeutic role of high levels of exogenous GDF15 in obesity and diabetes management." (PMID 30070999, 2018). "The high incidence in female knockout mice that showed much less robust phenotype than male mice in obesity development seems to suggest a direct GDF15 effect independent of obesity." (PMID 30070999, 2018). "Based on previous findings, these observations suggest that GDF15 expression in NAFLD occurs in a compensatory manner and that targeting this pathway may ameliorate obesity and related disorders." (PMID 30533221, 2018). "In accordance with aggravated obesity, cholesterol and triglyceride concentrations were also significantly elevated in mice lacking GDF‐15." (PMID 23316317, 2012). "The nonsteroidal anti-inflammatory drug (NSAID)-activated gene-1 (NAG-1), originally identified for its anticancer and anti-inflammatory properties, NAG-1 or GDF15 is now recognized as a multifunctional protein involved in various physiological processes such as obesity, aging, and liver diseases." (PMID 40316530, 2025). "Thus, the effectiveness of BS in reducing fat mass and resolving obesity-related comorbidities (such as T2D, HBP, or fatty liver) could lead to changes in both circulating GDF15 and its primary tissue source." (PMID 40530451, 2025). "In contrast, two studies examined, and found no clear relationship, between obesity and GDF15." (PMID 40019842, 2025). "Therefore, it is not surprising that conditions such as obesity and metabolic syndrome, now incorporated in the MASLD diagnostic flowchart, have been associated with significantly increased GDF15 plasma levels." (PMID 40650260, 2025). "Future studies should focus on elucidating the precise pathways through which GDF15 modulates EE and determining whether or not its long-term application can be harnessed for therapeutic purposes in obesity." (PMID 40837873, 2025). "In light of this, a valuable hypothesis beyond the controversial connection between GDF-15 and body weight is that the increase in GDF-15 is likely an adaptive mechanism against obesity, rather than a causative factor." (PMID 40283592, 2025). "This suggests that up-regulation in circulating GDF15 observed in obesity may not arise from adipose tissues in humans." (PMID 40837873, 2025). "Additionally, research on melanoma-derived GDF15 has shown that it can up-regulate thermogenic and lipolytic genes, leading to improved glucose tolerance and resistance to obesity independent of food intake." (PMID 40837873, 2025). "Not surprisingly, the Gdf15 KO mice demonstrate reduced metabolic rates, as indicated by their decreased levels of oxygen content and calorie production in comparison to the wild‐type mice in the diet‐induced obesity (DIO) model." (PMID 39700016, 2024). "In conclusion, GDF15 may represent a future target therapy for T2DM and obesity." (PMID 38668314, 2024). "Although GDF‐15 increased significantly and appetite perceptions were suppressed, energy intake did not significantly reduce postexercise in males with obesity, but there was no compensatory energy compared to the CTRL session in spite of expending energy during MICT." (PMID 39263536, 2024). "In study 1, we show that both fasting and postprandial GDF15 levels are unaffected by weight status in healthy individuals, whereas the levels of GIP are markedly elevated in leaner individuals compared with people with obesity and are robustly increased following a high-fat meal." (PMID 38762719, 2024). "Since exogenous Gdf15 injection ameliorated the obesity phenotype in obese animal models, therapeutic strategies targeting Gdf15 or its upstream regulator SIK2 in POMC neurons of the obese human brain will require the identification of differences in the Gdf15-GFRAL axis between the two species." (PMID 39329749, 2024).